GRXCR2 (glutaredoxin and cysteine rich domain containing 2)
Description:
Required for hearing (By similarity). Plays a role in maintaining cochlear stereocilia bundles that are involved in sound detection. Ensures the restriction of TPRN to the basal region of stereocilia in hair cells (By similarity).
Synonyms: DFNB101
Tractability: PROTAC: ubiquitination databases record sites on it.
Gene: Protein-coding gene on chromosome 5 (145,858,521 to 145,937,126, reverse strand). Ensembl gene ENSG00000204928.
Subcellular location: Cell projection, stereocilium
Pathways (Reactome):
Sensory Perception: Sensory processing of sound by inner hair cells of the cochlea; Sensory processing of sound by outer hair cells of the cochlea
Gene Ontology:
Biological process: sensory perception of sound
Cellular component: microvillus; stereocilium base; stereocilium shaft; stereocilium
Genetic constraint (gnomAD): Loss-of-function variants: 21 observed, 22.33 expected, observed/expected ratio (o/e) 0.94, 90% interval 0.67 to 1.35. The upper end of that interval is the gene's LOEUF score, 1.35, which puts it in group 5 of 6, group 1 being the genes least tolerant of losing a copy. Missense variants: 298 observed, 300.65 expected, observed/expected ratio (o/e) 0.99, 90% interval 0.9 to 1.09. Synonymous variants: 127 observed, 116.83 expected, observed/expected ratio (o/e) 1.09, 90% interval 0.94 to 1.26.
Gene-disease validity (ClinGen):
ClinGen rates the evidence that GRXCR2 causes each of these diseases.
nonsyndromic genetic hearing loss (autosomal recessive): Moderate.
Homologues: Orthologues: chimpanzee GRXCR2 (98% identical), dog GRXCR2 (88% identical), rabbit GRXCR2 (88% identical), guinea pig GRXCR2 (84% identical), pig GRXCR2 (83% identical), rat Grxcr2 (81% identical), mouse Grxcr2 (81% identical), macaque GRXCR2 (59% identical), tropical clawed frog grxcr2 (54% identical), Drosophila melanogaster CG12206 (23% identical), Drosophila melanogaster CG31559 (22% identical), Caenorhabditis elegans Y46E12A.3 (15% identical). Paralogues in human: GRXCR1 (33% identical), GLRX2 (8% identical).
Diseases named in the same sentence as GRXCR2 in open-access papers:
GRXCR2 is named in the same sentence as 6 diseases in open-access papers, as found by Europe PMC text mining. Sharing a sentence is not in itself a finding about the gene and the disease. The quoted sentences say what the papers report.
deafness (8 papers, 2016 to 2023). An inherited or acquired condition characterized by the complete loss of the ability to hear from one or both ears. "GRXCR2 mutations are rare causes of recessive deafness as there is only one report worldwide (Imtiaz, Kohrman, & Naz, 2014)." (PMID 32048449, 2020). "Since Grxcr2 mutations cause deafness, we characterized hair bundle morphology in Grxcr2D46/D46 and Grxcr2D85/D85 hair cells by staining whole-mount cochlea with phalloidin to detect F-actin in stereocilia." (PMID 30380417, 2018). "We screened a large panel of probands diagnosed with congenital, severe-to-profound, nonsyndromic deafness for evidence of GRXCR2 variants." (PMID 30157177, 2018). "However, reduced levels of taperin, which has also been linked to deafness, in Grxcr2-deficient mice restored their hearing and stereocilia morphology." (PMID 35672333, 2022). "Thus, our findings demonstrate that GRXCR2 restricts taperin to the stereocilia base, and that mislocalized taperin activity disrupts stereocilia morphogenesis to cause deafness." (PMID 30380417, 2018). "In addition to GRXCR2 and taperin, several proteins linked to deafness are concentrated at or near the stereocilia base, including Fam65b, PTPRQ, CLIC5, radixin, and PDZD7." (PMID 30380417, 2018). "Our demonstration of progressive hearing loss in mice carrying a hypomorphic Grxcr2 mutation suggests that similar mutations in human could also underlie later onset deafness." (PMID 30157177, 2018). "Moreover, the expression levels of the other nine deafness-related genes (Myo15, Gfi1, Lhx3, Barhl1, Pjvk, Tomt, Pou4f3, Tmc1, and Grxcr2) were downregulated more than 2-fold in DT-treated Prestin-hDTR mice." (PMID 30918314, 2019). "Recently, a homozygous frameshift mutation in human GRXCR2 was found to co-segregate with early onset hearing loss in a single consanguineous Pakistani pedigree, indicating the importance of the gene in human hearing and defining the DFNB101 deafness locus." (PMID 30157177, 2018). "We did not detect evidence of GRXCR2 pathogenic variants in a large screen of over 600 individuals with nonsyndromic hearing loss or in 120 individuals with Usher syndrome, suggesting that such variants are not a frequent cause of human deafness in these populations." (PMID 30157177, 2018). "Grxcr2 Δ/Δ mice do not exhibit circling or head shaking behaviors that are indicative of vestibular defects and that are often observed in mouse deafness mutants." (PMID 30157177, 2018). "Three deafness-related PSGs might also perform roles in balance and spatial orientation: PDZD7 and GRXCR2 are involved in morphogenesis of the sensory hair cells (‘stereocilia’) in the inner ear, and TECTA encodes a key protein of the tectorial membrane in which the stereocilia are embedded." (PMID 38066641, 2023).
hearing loss (7 papers, 2018 to 2022). "Mutations in human glutaredoxin domain-containing cysteine-rich protein 1 (GRXCR1) and its paralog GRXCR2 have been linked to hearing loss in humans." (PMID 34366792, 2021). "Human GRXCR2 is located on the long arm of chromosome 5 in band q32 within the candidate regions defined for two dominant, nonsyndromic hearing loss loci, DFNA42 and DFNA54." (PMID 30157177, 2018). "In one previously unresolved family, we found a homozygous frameshift PLP variant in GRXCR2 (OMIM: 615762), GRXCR2‐c.251delC (p.Arg84 frameshift), in two affected siblings; and additionally, in 1/80 unrelated individuals affected with non‐syndromic hearing impairment (NSHI)." (PMID 33528103, 2021). "The mechanism we present here, where GRXCR2 restricts taperin from entering the stereocilia shaft, may also explain the morphological defects and hearing loss caused by mutations of CLIC5, radixin, PTPRQ, MYO6, Fam65b, or other components located at the basal region of stereocilia." (PMID 30380417, 2018). "Disruption of the interaction between CLIC5A and GRXCR2 was found to have minimal effects on stereocilia morphogenesis, however, the disruption led to hearing impairment in mice." (PMID 36035115, 2022). "Here, we revealed an interaction between GRXCR2 and CLIC5, two proteins linked to hearing loss in humans." (PMID 34026762, 2021). "Mutations in GRXCR2 and GRXCR1 have been linked to hearing loss in humans, but the underlying mechanisms are still unknown." (PMID 30380417, 2018). "In one previously unresolved family, we found a homozygous frameshift PLP variant in GRXCR2 (OMIM: 615762), NM_001080516.1(GRXCR2):c.251delC p.(Ile85SerfsTer33), in two affected siblings; and additionally, in 1/80 unrelated individuals affected with non‐syndromic hearing impairment (NSHI)." (PMID 33528103, 2021).
GRXCR2 also shares sentences with these, for which no sentence is quoted: Hearing impairment (2 papers); genetic disease (1); retinitis pigmentosa (1); Usher syndrome (1).